FGF23 (fibroblast growth factor 23)
Diseases named in the same sentence as FGF23 in open-access papers (continued):
Sharing a sentence is not in itself a finding about the gene and the disease.
cardiac disease (28 papers, 2016 to 2024). "Another large study showed that an increased level of FGF23 was associated with subclinical cardiac disease, new HF, and a 14% greater risk of IHD." (PMID 37371618, 2023). "The main objective was to ascertain the potential use of plasmatic Klotho and FGF23 as markers for CKD-associated cardiac disease and mortality." (PMID 30934737, 2019). "Recent studies have shown that FGF23 not only is associated with the development of cardiac complications in patients with CKD but also may be independently associated with cardiac disease." (PMID 37593148, 2023). "Circulating FGF23 was associated with CH in patients with chronic kidney and heart disease." (PMID 35794561, 2022). "Furthermore, in future investigations, it would be valuable to assess the pathophysiological cardiac effects of FGF23 and elucidate whether FGF23 secretion causes heart disease or vice versa." (PMID 35736431, 2022). "There are many more questions to be answered regarding FGF23 effects upon cardiac structure and function: whether FGF23 secretion causes heart diseases or vice versa, whether FGF23 plays a special role in acute MI cases, and whether cardiomyocytes produce FGF23 in health and disease, for example." (PMID 34055103, 2021). "The current study shows that both Klotho and FGF23 are independently altered and associated with concentric hypertrophy in CKD patients, thus being suitable as indicators of cardiac disease in this population." (PMID 30934737, 2019). "Serum FGF15/19 levels are decreased and FGF21 and FGF23 levels are increased in heart diseases, which also suggests their roles in heart pathophysiology." (PMID 27803896, 2016). "The mechanism explaining the relationship between FGF23 and the development of cardiac disease remains unclear." (PMID 37593148, 2023). "Thus, the relationship between FGF23 and cardiac disease is fairly complex, and it would seem simplistic to attribute the observed associations between FGF23 and mortality to direct cardiac actions of FGF23." (PMID 36977891, 2023). "In line with the recent work of Drew and collaborators, the present work used a pool of 107 CKD patients to ascertain the potential use of plasmatic Klotho, FGF23 or both, as markers for CKD-associated cardiac disease and to discuss their eventual use as therapeutic targets in CKD." (PMID 30934737, 2019). "Thus, our data support a potential therapeutic role for DMP1 in CKD to reduce FGF23 and potentially attenuate bone and heart disease." (PMID 31044094, 2019). "Is modification of FGF23 a promising therapeutic option in cardiac disease?" (PMID 30013515, 2018). "Signaling disorders of FGF2, FGF21, and FGF23 as paracrine signals also result in heart diseases." (PMID 27803896, 2016). "Therefore, FGF23 might be a potential target to prevent cardiac disease in patients with CKD." (PMID 29611320, 2018). "In heart diseases, serum FGF15/19 levels or FGF21 and FGF23 levels decrease or increase, respectively, indicating their possible roles in heart pathophysiology." (PMID 27803896, 2016). "Taken together, we showed that besides the LV, FGF23 is also expressed in the right ventricle and thus, beside LVH, could play a role in other cardiac diseases." (PMID 35118076, 2021). "In addition, heart diseases affect serum levels of FGF15/19, FGF21, and FGF23, indicating that these FGFs are serum biomarkers for heart diseases." (PMID 27803896, 2016). "However, a reduction of FGF23 as a therapeutic option in kidney or cardiac disease is currently not appealing since the potential chronic effects of FGF23 inhibition are unpredictable in conditions with reactive, secondary FGF23 elevation." (PMID 33000285, 2021).
metabolic disorders (23 papers, 2009 to 2025). "The underlying metabolic disorder is caused by a mutation in a gene responsible for regulating fibroblast growth factor 23 (FGF23) activity." (PMID 40330379, 2025). "Further experimental studies are needed to shed more light on the underlying mechanisms between FGF23 and glucose and lipid metabolism, and prospective studies of large scale are needed to determine the association between FGF23 and metabolic disease, such as T2D." (PMID 31736870, 2019). "XLH is an inherited metabolic disorder of fibroblast growth factor 23 (FGF23) excess that creates an antagonistic environment to bone formation." (PMID 36849506, 2023). "Elevated FGF-23 levels lower Klotho expression, so its suppressing effect on klotho production can induce vascular and metabolic disorders." (PMID 36362179, 2022). "Current studies on the endocrine FGF family have demonstrated the importance of FGF19, FGF21, and FGF23 in human genetic and metabolic disorders, suggesting their therapeutic role in metabolic diseases." (PMID 34572066, 2021). "FGF23 is a bone-derived factor and plays a role in metabolic diseases." (PMID 32156311, 2020). "FGF23 is considered as a disease biomarker since elevated plasma levels are observed early in patients with acute and chronic disorders including renal, cardiovascular, inflammatory, and metabolic diseases." (PMID 29807981, 2018). "Thus, tissue specific modulation of FGFR1 is likely necessary for therapeutic intervention for metabolic diseases or psychiatric disorders, to gain efficacy without adverse side effects related to the FGF23-axis." (PMID 23451204, 2013).
kidney (13 papers, 2011 to 2026). "Taken as a whole, these results suggest that high FGF-23 levels contribute to the increased cardiovascular risk in kidney transplant recipients by impairing endothelial function." (PMID 29874852, 2018). "As we plan to analyze potential biomarkers for acute kidney injury in our clinical trial, we included FGF-23 in our customized magnetic bead panel." (PMID 38361581, 2024). "Overall, our findings suggest that the hepatic expression of FGF23 was upregulated in response to alcoholic liver injury." (PMID 38479224, 2024). "In our experimental CKD models with unchanged serum PTH and FGF23 levels, histological bone alterations seemed to increase concurrently with the extent of kidney injury." (PMID 37108433, 2023). "Chronic liver injury induced by a high fat diet or elevated bile acids also increased hepatic FGF23 levels." (PMID 35231062, 2022). "A larger study population along with well-designed and complementary biochemical experiments will be essential for clarifying whether FGF-23 and vitamin D metabolites are acting independently or in concert to affect colorectal carcinogenesis." (PMID 21383962, 2011).
skeletal dysplasia (7 papers, 2020 to 2026). Any Mendelian diseases that affects growth and development of the skeleton. "Cutaneous skeletal hypophosphatemia syndrome (CSHS) is a condition caused by somatic mutations in Ras and are characterized by excess FGF23 and skeletal dysplasias." (PMID 32547492, 2020).
heart (6 papers, 2015 to 2026). "Tumor-induced osteomalacia (TIO) is an ultra-rare disease caused mostly by benign tumors that secrete fibroblast growth factor-23." (PMID 37980279, 2023). "HFABP levels were significantly correlated to New York Heart Association classes and to established biomarkers of cardiac dysfunction and remodeling (amino-terminal pro-B-type natriuretic peptide [NT-proBNP], fibroblast growth factor 23, and galectin-3)." (PMID 37360894, 2023). "Tumour-induced osteomalacia (TIO), is a rare paraneoplasatic syndrome found in >95% of benign tumours that secrete fibroblast growth factor 23 - a phosphaturic circulating hormone." (PMID 29632597, 2016). "Since even mild CKD has been associated with marked increases in bone FGF23 expression, the increased bone FGF23 expression in the liver and heart transplant recipients may, similar to the renal transplant recipients, reflect the presence of both CKD and immune suppression." (PMID 26390291, 2015).
immune dysfunction (6 papers, 2012 to 2025). "A translational study demonstrated that FGF23 per se causes an immune dysfunction in experimental murine models and white blood cells obtained from healthy volunteers." (PMID 36828412, 2023). "Elevated titers of FGF23 are associated with increased inflammation in patients, and increased levels of FGF23 induce immune dysfunction in experimental murine models and human white blood cells in vitro." (PMID 36828412, 2023). "Increased levels of FGF23 have been related to increased inflammation in patients while inducing immune dysfunction in human white blood cells in vitro and in experimental models." (PMID 37637614, 2023).
endocrinopathies (4 papers, 2012 to 2025). "Apart from endocrinopathies, some cases are characterized by excessive fibroblast growth factor 23 (FGF23) production from abnormal fibro-osseous tissue in FD lesions, resulting in increased renal phosphate excretion." (PMID 40297189, 2025).
inflammation (4 papers, 2012 to 2025). Aberrant reaction of the microcirculation characterized by movement of fluid and leukocytes from the blood into extravascular tissues. "We also identified additional FGF23-responsive transcripts and activation of networks associated with renal damage and chronic inflammation, including lipocalin 2 (Lcn2), transforming growth factor beta (TGF-β) and tumor necrosis factor-alpha (TNF-α) signaling pathways." (PMID 22970174, 2012). "Given their roles in mineral metabolism, it is plausible that the systemic alterations in FGF23 and iPTH in CKD patients are more reflective of the underlying renal pathology than of localized periodontal inflammation." (PMID 39176315, 2024).
bacterial infections (3 papers, 2012 to 2024). "Taking together, Phex mutation primarily up-regulates gene expression levels in FGF23 mediated pathways in the middle ears, resulting in cell proliferation and defence impairment at the mucosae and subsequently bacterial infection." (PMID 23028440, 2012). "In our study, only patients with bacterial infections presented statistically significant slightly reduced serum calcium and phosphate values compared to controls, as well as significantly lower i-FGF23 and higher hepcidin levels." (PMID 39336155, 2024). "Further research is required to understand the role of FGF23 in the hepcidin–ferroportin axis and for hepcidin in the diagnosis of bacterial infections and mineral metabolism." (PMID 39336155, 2024). "Previous studies found that FGF23 regulates the immune response and host defense against bacterial infections." (PMID 36649363, 2023). "Paradoxically, the lower serum Pi levels of the patients with bacterial infections are not in accordance with their low i-FGF23 values." (PMID 39336155, 2024). "As application of azithromycin from G18 to P35 failed to prevent OM in Hyp-Duk/Y mice, we concluded that bacterial infection was secondary to the primary pathological alteration mediated by FGF23/PGE2 in middle ears." (PMID 23028440, 2012).
infectious disease (3 papers, 2012 to 2024). A disorder directly resulting from the presence and activity of a microbial, viral, or parasitic agent in humans. "Basic studies revealed that FGF23 directly inhibited neutrophil recruitment and calcitriol synthesis in macrophages, both of which are critical for the prevention of infectious diseases in hemodialysis patients." (PMID 30061632, 2018). "Infectious diseases: FGF23 has also been suggested to be a regulator of innate immunity." (PMID 38846254, 2024). "We also evaluated the more recent non-cardiac impacts of FGF23 on the immune system, infectious disorders, and the unintentionally discovered gender-based FGF23 variation that requires more research." (PMID 38846254, 2024).
musculoskeletal disorder (3 papers, 2023 to 2025). "Furthermore, similar FGF-23 disturbance has been observed in other types of musculoskeletal disorders." (PMID 37686090, 2023).
psychiatric disorder (3 papers, 2013 to 2024). A disorder characterized by behavioral and/or psychological abnormalities, often accompanied by physical symptoms. "The primary objective of our study was to use bidirectional two-sample MR and MVMR analysis to explore the causal associations between calcium homeostasis markers (calcium, 25OHD, PTH, and FGF23) and nine psychiatric disorders." (PMID 37764834, 2023).
hematologic malignancies (2 papers, 2023 to 2025). "Rarely, non-PMT solid or hematologic malignancies may also produce excess FGF23." (PMID 39755803, 2025).
retinopathy (2 papers, 2020 to 2024). "Patients with progression of retinopathy as compared to those without were similar in clinical features including HbA1c, serum phosphate, FGF-23, vitamin D levels, demographics and traditional risk factors for retinopathy." (PMID 33225726, 2020). "This study was clinical in nature and did not investigate the underlying mechanism of the Klotho/FGF23 axis on retinopathy progression." (PMID 38374169, 2024). "We also measured several emerging markers of retinopathy risk such as VCAM-1, ox-LDL, hsCRP in a sub-group of patients and other hormones associated with Klotho such as FGF-23 and vitamin D which were not significantly different between groups." (PMID 33225726, 2020).
connective tissue diseases (1 paper, 2018). "Therefore, in the settings of connective tissue diseases and perhaps also other inflammatory states, the α-Klotho level may be determined by the balance between reduced Klotho synthesis caused by VD deficiency and inflammation and direct activity of FGF23." (PMID 30562918, 2018).
muscular disorders (1 paper, 2025). "We, therefore, hypothesized that FGF23 is directly involved in the muscular disorders that characterize XLH, and clarifying these effects at the molecular and cellular level is essential to elucidate XLH pathogenesis and, consequently, its management." (PMID 40926139, 2025).
neurodegenerative disease (1 paper, 2021). A disorder of the central nervous system characterized by gradual and progressive loss of neural tissue and neurologic function. "Our findings identify ALS as another neurodegenerative disease linked to FGF23, and it will be of great interest in future studies to determine its contribution to disease progression." (PMID 34103575, 2021).
parathyroid gland (1 paper, 2025). "Physiological adaptation to altered levels of calcium, vitamin D, and fibroblast growth factor 23 (FGF23) leads to parathyroid gland hyperplasia and the increased production of parathyroid hormone (PTH)." (PMID 39860385, 2025).
peripheral neuropathy (1 paper, 2020). A disorder affecting the peripheral nervous system. "Peripheral neuropathy is associated with higher concentrations of circulating FGF-23, whereas patients treated with GLP-1 analogues or insulin have lower levels of circulating FGF-23." (PMID 32998751, 2020).
urinary tract diseases (1 paper, 2025). "In contrast, FGF-23 levels were strongly influenced by comorbidities, particularly urinary tract diseases (F = 72.330, p < 0.001) and joint degeneration (F = 550.575, p < 0.001)." (PMID 40943671, 2025).
FGF23 also shares sentences with these, for which no sentence is quoted: hypertrophy (12 papers); Hyperphosphatemic familial tumoral calcinosis (7); Ventricular hypertrophy (6); acute myocardial infarction (5); dialysis (5); Alzheimer disease (4); autosomal recessive hypophosphatemic rickets type 2 (4); inflammatory bowel disease (4); -dependent (3); calcium-phosphorus metabolic disorder (3); Hepatic fibrosis (3); hypercortisolism (3); hypertrophic cardiomyopathy (3); Infertility (3); polycystic ovary syndrome (3); scoliosis (3); small cell carcinoma of the lung (3); ST Elevation Myocardial Infarction (3); acute lymphoblastic leukemia (2); acute respiratory distress syndrome (2); cardiac arrhythmia (2); colon adenocarcinoma (2); Crohn disease (2); Cushing syndrome (2); dyslipidaemia (2); essential hypertension (2); Hearing impairment (2); hyperostosis (2); idiopathic hypercalciuria (2); Impaired glucose tolerance (2).
A further 131 diseases each share a sentence with FGF23 in 2 papers or fewer.